BZW1 (basic leucine zipper and W2 domains 1)
Description:
Translation initiation regulator which represses repeat-associated non-AUG (RAN) initiated translation probably by acting as a competitive inhibitor of eukaryotic translation initiation factor 5 (EIF5) function. Enhances histone H4 gene transcription but does not seem to bind DNA directly.
Synonyms: 5MP2; BZAP45; KIAA0005; Nbla10236
Tractability: PROTAC: UniProt records ubiquitination sites on it; ubiquitination databases record sites on it; its protein half-life has been measured.
Gene: Protein-coding gene on chromosome 2 (200,810,594 to 200,827,338, forward strand). Ensembl gene ENSG00000082153.
Subcellular location (Human Protein Atlas): Vesicles
Gene Ontology:
Molecular function: cadherin binding; RNA binding
Biological process: regulation of translational initiation
Cellular component: cytoplasm; membrane
Genetic constraint (gnomAD): Loss-of-function variants: 3 observed, 41.72 expected, observed/expected ratio (o/e) 0.0719, 90% interval 0.032 to 0.19. The upper end of that interval is the gene's LOEUF score, 0.19, which puts it in group 1 of 6, group 1 being the genes least tolerant of losing a copy. Missense variants: 185 observed, 396.19 expected, observed/expected ratio (o/e) 0.47, 90% interval 0.41 to 0.53. Synonymous variants: 130 observed, 126.88 expected, observed/expected ratio (o/e) 1.02, 90% interval 0.89 to 1.18.
Homologues: Orthologues: chimpanzee BZW1 (100% identical), mouse Bzw1 (100% identical), pig BZW1 (100% identical), rat Bzw1 (100% identical), macaque BZW1 (99% identical), dog BZW1 (99% identical), guinea pig Bzw1 (99% identical), tropical clawed frog bzw1 (93% identical), zebrafish bzw1a (86% identical), zebrafish bzw1b (79% identical), Drosophila melanogaster kra (52% identical). Paralogues in human: BZW2 (72% identical).